IL2 (interleukin 2)
Diseases named in the same sentence as IL2 in open-access papers (continued):
Sharing a sentence is not in itself a finding about the gene and the disease.
tumor (continued). "Standard protocols for ex vivo expansion of tumor infiltrating lymphocytes for adoptive cell therapy (ACT) traditionally used high dose IL-2 to facilitate T cell proliferation." (PMID 33178203, 2020). "The levels of IL-2 expression were significantly higher in PTC+HT or PTC tumor tissues (T) than in adjacent para-tumor tissue (PT) (P < 0.001)." (PMID 32368308, 2020). "Various groups, including our own, have worked on the concept of fusing the IL2 moiety with suitable tumor-homing antibodies, in order to concentrate the payload at the site of disease, helping spare normal tissues." (PMID 33110477, 2020). "We recently showed that the expression of soluble γc receptor (sγc) in T cells is highly upregulated upon TCR stimulation and inhibits the anti-tumor response of CD8+ T cells via regulating IL-2 and IL-15 signaling." (PMID 32731404, 2020). "Several studies supported the notion that exosomal PD-L1 inhibited IL-2 release and killing of tumor cells by T cells." (PMID 32493964, 2020). "We found that tumor-infiltrating T cells were expanded in the presence of exogenous IL-2 with upregulated surface expression of TIM-3 and PD-1." (PMID 32616706, 2020). "Both IL-2 and IL-10 were found to increase the cytotoxic activity of anti-tumor CD8+ T cells in vitro, suggesting a potential synergistic effect for the two cytokines." (PMID 32013102, 2020). "B10-(CD3xJB8) showed cytotoxicity against HLA-A24(+)/DNAJB8(+) tumour cells; however, the frequencies of IL-2 and IFNγ-secreting cells were lower than those of TNFα." (PMID 32753678, 2020). "IL-21 has also been reported to suppress antigen-induced differentiation of CD8+ T-cells, and enhance anti-tumour activity when compared to IL-2 and IL-15." (PMID 32824734, 2020). "Pro-inflammatory cytokines like interleukin- (IL-) 6 or IL-2 mainly attract and activate other inflammatory cells in the tumor microenvironment." (PMID 32298379, 2020). "Compared with non-tumor tissues, we found that IL-2 expression was up-regulated in PTC tissues, particularly in PTC+HT tissues and correlated positively with HLA-class I, CD3 and CD8 expression in PTC+HT tissues." (PMID 32368308, 2020). "TIM-3 was established as a negative regulator of T cell anti-tumor responses due to its association with an exhausted T cell state marked by the progressive loss of these cells’ ability to express IFN-γ, TNF-α and IL-2." (PMID 32858904, 2020). "Drug delivery and release from the tumor collagen matrix-DDS interaction improved safety by eliminating antibody hepatotoxicity and by ameliorating pulmonary edema by IL-2, and it also improved efficacy through reducing the size of tumor." (PMID 32133350, 2020). "The ligand of this receptor, PD-L1 is expressed on stromal and tumour cells and upon binding downregulates T-cell activation, proliferation and IL-2 production thereby limiting anti-tumour responses." (PMID 33036547, 2020). "In 1998, IL-2 was FDA-approved as an immunomodulating treatment (activating anti-tumor immune responses) of metastatic melanoma patients, which was due to its ability to mediate durable objective responses." (PMID 32899183, 2020). "The HATMSC2-MVs used in this study affect both histologically different cell lines, the ES-2 cells and the OAW-42 cells, by increasing the production of tumor-suppressive cytokines, such as IL-1ra, IL-2, IL-2Ra, IL-12-p40, IL12-p70, IL-15, and IFN-γ." (PMID 33266317, 2020). "To address how MSCs impact a tumor specific CAR T cell attack, we engineered T cells with a second generation CD28Δ-ζ CAR that is deficient in IL2 secretion due to a mutation in the lck binding domain of CD28." (PMID 32260097, 2020). "The treatment of released AP moiety increased the expression of IL-2, while that of IL-10 was decreased, showing potential in restoring Th1/Th2 immune balance in tumor microenvironment." (PMID 32646040, 2020).
tumor (continued). "In the CCR4‐IL2 IT group, no tumor cell areas were identified in the examined section of the liver, demonstrating that both the IL2‐CCR4 and CCR4‐IL2 bispecific ITs more effectively depleted the human CD25+CCR4+ tumor cells than IL2 fusion toxin or CCR4 IT." (PMID 32107846, 2020). "Hierarchical clustering of the most variable genes demonstrated that ACT + NKTR-214 induced far greater gene expression in tumor samples than ACT + IL-2 treatment." (PMID 32005809, 2020). "H-1PV treated patients displayed an increase in tumor-infiltrating cytotoxic T cells, induction of cathepsin B, and the expression of IFN-γ and IL-2, among other cytokines within the tumor microenvironment." (PMID 33066689, 2020). "Early studies tested tumor regressive properties of lymphokine activated CD3−CD56+ cells (or LAKs) injected in combination with IL-2." (PMID 32655841, 2020). "Moxa-grain-moxibustion has been shown to promote the production of IL-2 which can promote the proliferation of lymphocytes in tumor-bearing mice." (PMID 33456484, 2020). "Immunomodulation potential of rAF-IL12 in the HT29 tumor-challenged mice was carried out by measuring the expression levels of IL-12, IL-2 and IFN-γ cytokines." (PMID 33354412, 2020). "While such cytokine approaches promote tumor regression mechanistically, IL-2 and IFN-α both provided limited clinical efficacy, with a median OS of approximately one year and durable responses in the range of only 5–7%." (PMID 32429554, 2020). "In that situation the MSCs needed to provide both costimuli CD80 and 4-1BB in order to induce T cells for antigen-dependent IL2 release and tumor cell killing." (PMID 32260097, 2020). "Specifically, melatonin can limit tumor growth by increasing natural killer cell activity and counteracting tumor immune evasion by increasing IL-12, IL-2, and INF-γ production in T cells and monocytes, therefore driving T cells toward a Th1 response." (PMID 33302582, 2020). "In contrast, the proportion of CD8+ T cells was increased in TIL cultures when anti-CTLA-4 antibody was added to the tumor fragments during the initial TIL growth compared to TIL outgrowth when cultured only with IL-2." (PMID 32127601, 2020). "In the IL2 fusion toxin group, fewer tumor cell areas were seen in the examined section of the liver compared to those of the C21 IT group." (PMID 32107846, 2020). "The treatment of tumor-bearing animals by HA stimulates the murine peritoneal macrophages and neutrophils and also activates splenocytes and increases the secretion of IL-2 at the initial and later stage of the tumor growth." (PMID 34466583, 2020). "In a lung tumor model, where cancers were driven by HPV16, IL-2 therapy in conjunction with Aza treatment caused dramatic CD8+ T cell infiltration, which was required for anti-tumor efficacy, similar to the latter results of our study." (PMID 32296439, 2020). "The results from this comparative study demonstrate that the combined stimulation of γδ T cells via IL-2/IL-12/IL-18 is the most potent stimulus to enhance anti-tumor activity, proliferation and IFN-γ production in γδ T cells in the absence of TCR ligation." (PMID 31947966, 2020). "Percent of IFN-γ/IL-2 secreting CD4+ T cells specific to this autoepitope positively correlated with the tumor size." (PMID 32570805, 2020). "The isolated NK cells were firstly stimulated with cytokines (IL-15, IL-12 and IL-2) for 7 days and their cytotoxic function was then evaluated via a 6-h co-culture with a NK sensitive tumor cell line, K562." (PMID 33036556, 2020). "IFN-γ had a tumor cell-killing effect 47, while IL-2 was involved in facilitating CD8+ T cell differentiation and activation." (PMID 32226302, 2020). "Anti-inflammatory and immunomodulatory properties of the extract of A. paniculata and andrographolide have been linked to the increasing proliferation of lymphocytes and the production of IL-2 and inhibition of the tumor cell proliferation immune system." (PMID 33071794, 2020).
tumor (continued). "Only IFN-α and IL-2 as high-dose therapy have been approved for the systemic treatment of several cancers, based on moderate beneficial anti-tumor effects in clinical trials." (PMID 32917034, 2020). "Effective tumor immunotherapy requires four parts as follows: a tumor antigen targeting antibody, recombinant interleukin-2 with an extended half-life, anti-PD1, and a powerful T cell vaccine." (PMID 32746880, 2020). "Regarding RH30, at a high E:T ratio of 5:1, a significant reduction in tumor growth by γδ T cells was seen after all cytokine treatments with TCR stimulus with the combination of IL-2/IL-12/IL-18 leading to the highest reduction of impedance." (PMID 31947966, 2020). "As expected, 161519 TriKE combined with IL-2 treatment significantly delayed tumor growth and prolonged the survival of xenografted mice compared with that observed in controls." (PMID 33299651, 2020). "Expression of TNF-alpha and IL-2 attracts T cells to the tumor and also enhances their infiltration into the cancer cells." (PMID 33053757, 2020). "IL-2 is required for T cell growth and survival and TNFa is a potent inducer of T cell trafficking and tumor apoptosis." (PMID 32600470, 2020). "The addition of IL2 to the treatment regimen can increase the effectiveness of therapy due to the induction of expansion of tumor antigen presented T-cell." (PMID 32582698, 2020). "Here, the authors demonstrate that an engineered interleukin-2 promotes intratumoral T regulatory cell depletion while enhancing effective anti-tumour CD8+ T cell responses that result in potent tumor suppression." (PMID 32005826, 2020). "FACS analysis revealed that tumor‐infiltrating CD8+ T cells in the MB treatment group secreted more IL‐2, granzyme B, and perforin (Fig EV4E)." (PMID 32391629, 2020). "Mice receiving ACT + NKTR-214 showed a median tumor growth delay (evaluated as time to reach a tumor volume of 1000 mm3) of 42 days compared to ACT + IL-2 or ACT + vehicle (19.5 and 11 days, respectively)." (PMID 32005809, 2020). "CTLA-4 blockade promoted TIL growth from tumor fragments of 13 out of 14 (93%) patients compared to TIL growth from 9 out of 14 (64%) patients when tumor fragments were cultured in standard IL-2 conditions." (PMID 32127601, 2020). "It is interesting to note that in a co-culture with hADSCs-IL2 the inhibition of SH-SY5Y tumor cell growth was clearly observed compared to co-cultures of SH-SY5Y cells with native hADSCs or hADSCs-BFP." (PMID 32560387, 2020). "Anti-tumour properties of IL-2 are mediated by the cellular immune system, but IL-2 itself has no direct effect on tumours." (PMID 33014130, 2020). "The purported mechanism is through IL2-mediated sensitization of the tumor microenvironment to increase PD-L1 expression and increase CD8+ T cell infiltration, thus increasing the anti-PD-1 treatment efficacy." (PMID 32455916, 2020). "High levels of serum IL-2, IL-10, and IL-12 are correlated to the aggressive tumor characteristics in patients with DTC." (PMID 32655554, 2020). "T cells cocultured with IL-10-stimulated cells of K1 and TPC-1 exhibited increased cell activation (%CD25+ of CD3+ T cells) and IL-2 production at an E:T ratio of 30:1, which was evidence for promotion in tumor immunity in PTC." (PMID 32348468, 2020). "Long-term incubation of lymphocytes with IL-2 induces their differentiation into LAK cells cytotoxic against tumor cells." (PMID 33291689, 2020). "Nevertheless, tumour immune escape and malignant growth will happen if aberrant responses of IL‐2 occurs." (PMID 31742861, 2020). "Tumor growth was significantly suppressed, the percentage of Tregs was reduced in tumor and spleen, and tumor‐infiltrating lymphocytes showed increased secretion of the effector cytokines IL‐2 and IFN‐γ." (PMID 32578942, 2020). "The results showed that all these subpopulations acquired the ability to kill K562 tumor cells after treatment with IL-2." (PMID 33291689, 2020).
tumor (continued). "In mice genetically modified tumor cells engineered to express cytokines like interleukin 2 (IL-2), interferon gamma (IFN-y) or GM-CSF can be rejected and can induce systemic immunity." (PMID 32365838, 2020). "In conclusion, IL-2 up-regulated HLA-class I expression and enhanced anti-tumor T cell immunity during the development of PTC and HT." (PMID 32368308, 2020). "This therapeutic approach consists of isolating TILs from the patient’s tumor and expanding them ex vivo using interleukin-2 (IL-2) activation, before re-injection into the autologous patient to induce a CTL-dependent immune response." (PMID 32899183, 2020). "IL-2 can regulate the cellular activity of leukocytes in the immune system, react with antibodies, hematopoiesis and tumor surveillance, and induce killer cells to produce cytokines such as IFN-γ and TNF-α." (PMID 32425919, 2020). "The fundamentals of cytokine gene therapy relies on the increase of cytokine levels with anti-tumor properties, including interleukin-2 (IL-2), IL-4, IL-6, IL-12, IL-24, interferon-alpha (IFN-α), IFN-γ, IFN-β or tumor necrosis factors (TNF) TNF-α and TNF-β." (PMID 32151052, 2020). "The targeted delivery of interleukin-2 to the tumor is gaining attention as an avenue to potentiate the action of T and NK cells at the site of disease." (PMID 33110477, 2020). "Each γc cytokine has been evaluated for augmentation of T-cell anti-tumour immune responses, building on the early work with tumour infiltrating lymphocyte expansion, performed in the presence of high concentration IL-2." (PMID 32824734, 2020). "Expression of anti-tumour cytokines, including TNFα, IL2, and IFNγ in sorted CD8+ cytotoxic cells, were measured by quantitative real-time PCR." (PMID 31913856, 2020). "Interleukins such as IL-2 and IL-10 were correlated to tumor aggressiveness and to serum Tg level, which suggests the involvement of interleukins would improve the efficiency of Tg evaluation system." (PMID 32655554, 2020). "The group compared the efficacy of IL-2 fusion toxin with developed anti-human CCR4 immunotoxin (CCR4 IT) and demonstrated that CCR4 IT showed greater tumor response in a CD25 + CCR4 + CTCL mouse model than IL-2 fusion toxin." (PMID 33384022, 2020). "The most significant biological processes that appear to negatively correlate with the immune risk are IFN-α responses, IFN-γ responses, IL-2/STAT5 signaling and IL-6/JAK/STAT3 signaling, all of which were associated with tumor immunity." (PMID 31988638, 2020). "First, binding of scDbEpCAMxCD3 to these tumor cell lines was determined by flow cytometry and T cell activation measured in co-culture assays by IL-2 release." (PMID 32504247, 2020). "In order to evaluate the relative cytokine serection capacity, we collected the supernatants for the detection of IFNγ and IL-2 secretion levels after 24 hours coculture of tumor and CAR-T cells." (PMID 32685008, 2020). "In light of this, we investigated if the cytotoxic advantage of IL-2/IL-15-expanded Vγ9Vδ2 T cells was maintained in hypoxia, a state more representative of the tumor microenvironment in vivo." (PMID 32983105, 2020). "Although early studies established the proof of concept of the therapeutic anti-tumor potential of IL-2, the responses were limited and its toxicity was substantial when used at high doses." (PMID 32013092, 2020). "Here, definitely the presence and availability in the tumor microenvironment of sufficient amounts of key cytokines, such as IL-2 and IFNɣ produced by anti-tumor primed CD4+ T cells, facilitated the activation and function of CD8+ CTL effectors." (PMID 33138029, 2020). "In many cases, tumor cells are genetically modified to add functions, such as cytokine production (e.g., IL-2 and granulocyte-macrophage colony-stimulating factor (GM-CSF)) and costimulation (e.g., B7-1)." (PMID 33282961, 2020). "In general, CAR-T cells would kill tumor cells accompanied with the release of cytokines, including IL-2, IL-4, IL-6, IFNγ, and TNFα." (PMID 31998790, 2020).
tumor (continued). "Due to its originally described effect as an autocrine survival and proliferation signal for T cells and the indispensable role of T cells in anti-tumor immunity, IL-2 was explored in cancer therapy early after its discovery." (PMID 32917054, 2020). "Caserta at al. reported that IL-7 was superior to IL-2 for expansion of tumour-reactive CD4+ T cells." (PMID 32183246, 2020). "In the future, the right amount of stimulation by IL-2 and preservation of the original tumor environment needs to be carefully determined, in particular when optimizing this platform toward prediction of responses to ICI." (PMID 33072556, 2020). "These ATL-21C T-cell lines showed to have made growth progression from IL-2-dependent to IL-2-independent growth phase and further evolved into tumor-producing cancer cells in immunodeficient mice as the same clonal lines." (PMID 32210945, 2020). "IL-2 is also widely used for ex vivo expansion of tumor-infiltrating lymphocytes (TILs) or CAR-T cells in adaptive T cell therapy." (PMID 33266177, 2020). "In keeping with previous studies, neutralization of IL-2 abolished the anti-tumor activity of αCTLA-4." (PMID 31924474, 2020). "Mice treated with rAV/CIITA/IFN-γ + rAV/IL-2 + rAV/Ii-RGC showed tumor regression in three of four animals." (PMID 32079263, 2020). "The procedure starts with multi-well cultures of tumor fragments or single-cell suspensions obtained from disaggregated tumors, in the presence of high dose of IL-2." (PMID 32423420, 2020). "CTLA-4 competes with CD28 for the B7 ligand, inhibiting T cell proliferation and IL-2 secretion, and has been shown to inhibit tumor cell proliferation." (PMID 35582437, 2020). "Without TCR stimulus, only the cells exposed to combination treatment of IL-2, IL-12 and IL-18 had an effective suppressive effect on tumor growth even at a low E:T ratio, i.e., of 0.5:1." (PMID 31947966, 2020). "The use of TILs for cancer treatment is achieved by harvesting CD4+ and CD8+ T lymphocytes from the patient’s tumor, followed by in vitro expansion in a medium supplemented with IL-2 alone or in combination with IL-7, IL-15, and IL-21." (PMID 33287392, 2020). "Tumor cells were co-cultured with interleukin-2 (IL-2) activated pre-treated cytotoxic TAL-104 T-cells to evaluate T-cell-mediated killing via quantification of dead/live tumor cells." (PMID 32655895, 2020). "With co-delivery of PTX and IL-2 to the tumor region, the low-dosage of PTX release triggered the calreticulin (CRT) exposure on tumor cells and further induced the infiltration of CD8+ T cell into tumor tissue." (PMID 32210184, 2020). "IL-2 has been shown to regulate the balance between Tregs and Th17 cells in a tumor, reducing the percentage of Th17 cells in the TME and increasing the number of Tregs." (PMID 32148497, 2020). "In the in vivo part of our studies, we aimed to address key questions such as (i) is HSP70\IL-2 treatment sufficient to facilitate recruitment of NK cells into the tumor site?" (PMID 32218162, 2020). "Tumor-infiltrating T, B, and NK cell levels and plasma concentrations of Th1 (IL-2, IFN-γ, and TNF-α), Th2 (IL-4, IL-5, IL-6, and IL-10), Th9 (IL-9), and Th17 (IL-17A, IL-17F, IL-21, and IL-22) cytokines were evaluated." (PMID 32802733, 2020). "For example, incorporation of interleukin-2 (IL-2) gene in NDV causes a stable expression of the cytokine, which eventually stimulates the T-cell response hence, increase the viral anti-tumour capacity." (PMID 32612457, 2020). "IL2 in high doses is clinically approved as a cancer therapy because of the desired anti-tumor effects of Teffs." (PMID 32111171, 2020). "NKTR-214 shows superior anti-tumor activity over native IL-2 and systemically expands anti-tumor CD8+ T cells while inducing Treg depletion in tumor tissue but not in the periphery." (PMID 32005826, 2020).